BMI1 (BMI1 proto-oncogene, polycomb ring finger)
Diseases named in the same sentence as BMI1 in open-access papers (continued):
Sharing a sentence is not in itself a finding about the gene and the disease.
oral squamous cell carcinoma (19 papers, 2007 to 2026). "Tumor growth was also suppressed by inhibiting BMI1 pharmacologically in HNSCC and targeting BMI1 related CSC in oral squamous cell carcinoma (OSCC) has been shown as a clinically relevant anticancer therapy." (PMID 34359786, 2021). "The cell lines established from oral squamous cell carcinomas (OSCC) also expressed notably higher level of Bmi-1 compared with those of normal human oral keratinocytes (NHOK)." (PMID 17179983, 2007). "Bmi-1 protein and RNA expression levels were markedly enhanced in the cells of oral squamous cell carcinomas (OSCC) compared with that of normal human oral keratinocytes (NHOK)." (PMID 17179983, 2007). "Moreover, it was reported that knockdown of Bmi-1 using siRNAs inhibited the tumor initiation of oral squamous cell carcinoma CSCs/CICs." (PMID 26751205, 2016). "The polycomb complex protein BMI‐1 is frequently overexpressed in HNSCC and increased BMI‐1 expression was associated with cervical node metastasis, Ki-67 abundance, and reduced OS and also served as an independent prognostic factor for patient outcomes in oral cavity SCC." (PMID 32588101, 2021). "Moreover, miR-494-3p could induce the radiosensitivity of oral squamous cell carcinoma by downregulating Bmi1." (PMID 30518388, 2018). "In this study, we analyzed immunoreactive protein and relative gene expression of ABCG2 and Bmi-1 in a panel of eight cell lines derived from oral tissues with a spectrum of diseases ranging from normal through mild and moderate/severe dysplasia to oral squamous cell carcinoma (OSCC)." (PMID 24415717, 2014). "In oral squamous cell carcinoma (OSCC), m6A methylation of the 3′UTR region of the cancer stem cell marker BMI1 enhancers BMI1 translation by binding to IGF2BP1, leading to an increase in polysome-bound BMI1 mRNA." (PMID 38444581, 2024). "In oral squamous cell carcinoma, METTL3 promotes tumorigenesis and metastasis through BMI1 m6A methylation." (PMID 35399719, 2022). "Paraffin-embedded tissue blocks of 28 specimens of Non-dys OL, 33 of Dys OL, 9 of normal oral mucosa (NOM), 17 of inflammatory hyperplasia (IH), and 19 of oral squamous cell carcinomas (OSCC) were stained for Ki-67 and BMI-1 using immunohistochemistry." (PMID 32348447, 2020). "Thus, by deleting BMI1 in this human oral squamous cell carcinoma (OSCC) model, we confirmed that BMI1 increases multiple markers early in 4-NQO–induced tumorigenesis." (PMID 41385756, 2026). "In oral squamous cell carcinoma, METTL3 increases IGF2BP1-dependent mRNA m6A methylation of B cell-specific Moloney murine leukemia virus integration site 1 (BMI1), a polycomb complex protein, thus promoting its mRNA translation by recruiting polysomes to BMI1 mRNA." (PMID 40584294, 2025). "Up-regulation of METTL3 expression in oral squamous cell carcinoma (OSCC) promotes OSCC cell proliferation, self-renewal, migration, and invasive processes, mainly through BMI1 m6 A methylation at the post-transcriptional level to facilitate the translation of BMI1 in OSCC." (PMID 39289775, 2024). "Expression of ABCG2 and Bmi-1 was rigorously evaluated in a collection of eight oral cell lines originating from normal tissue (OKF6-TERT2), mild dysplasia (DOK), severe dysplasia (POE-9n), and oral squamous cell carcinoma (PE/CA PJ15, SCC04, SCC25, SCC09, and SCC15)." (PMID 24415717, 2014).
liver cancer (18 papers, 2012 to 2025). An epithelial or non-epithelial malignant neoplasm that arises from the liver. "Encapsulating PTC‐209, a BMI1 inhibitor, in liposomes and delivering it to liver cancer tissues with radiation resistance can restore the sensitivity of liver cancer cells to radiation therapy." (PMID 40665579, 2025). "The BMI1 gene is an important factor in promoting radiation resistance and exacerbating poor prognosis in liver cancer patients." (PMID 40665579, 2025). "Subsequent studies reported that NP treatment disrupts the spherical formation of cancer stem cells, which are the cause of metastasis in liver cancer, and reduces stem cell markers such as SOX2, BMI-1, Nanog and c-Myc by inhibiting stem cell genes." (PMID 39459502, 2024). "Later, studies reported that NP treatment disrupted the spherical formation of cancer stem cells, which is the cause of metastasis in liver cancer, and by reducing the expression of stem cell genes such as SOX2, BMI-1, Nanog, and c-Myc." (PMID 39356934, 2024). "Another study has demonstrated that SNHG3 in liver cancer cells can regulate BMI1 through ceRNA mechanism, thereby affecting the malignant behavior of liver cancer." (PMID 36208024, 2023). "CD44, CD90, CD133, and EpCAM are the cell–surface markers of liver cancer stem cells, further, Oct-4 and BMI-1 are the key ‘stemness’ genes in CSCs from various cancers." (PMID 24806207, 2014). "Our study also provides the evidence, for the first time, that Bmi1 expression is required for liver cancer development in vivo, thus representing a promising target for innovative treatments against human liver cancer." (PMID 23029524, 2012). "Our current study adds to all these previous studies, providing further evidence that Bmi1 functions as an oncogene and is required for liver cancer development." (PMID 23029524, 2012). "Given the growing clinical interest in YAP1-targeted therapies, understanding how SALL4 and BMI1 interact within the YAP1 signaling pathway may help refine treatment strategies for aggressive liver cancers." (PMID 40932240, 2025). "In this study, we considered that BMI1 may be key to unlocking the role of Schistosoma infection in the development of liver cancer." (PMID 38515119, 2024). "Therefore, confirming that BMI1 is a crucial factor involved in schistosomiasis-induced liver cancer is very important." (PMID 38515119, 2024). "BMI1 was first identified as an oncogenic effector for the development of lymphocytic leukemia by suppressing c-Myc, which is dysregulated in multiple cancer types, such as colon, lung and liver cancers." (PMID 32987767, 2020). "Additionally, BMI1 is involved in the maintenance of the tumorigenic SP subpopulation in liver cancer." (PMID 32987767, 2020). "BMI1 has been found to regulate the self-renewal of hepatic cancer stem cells." (PMID 28445151, 2017). "Altogether, these studies suggest that targeting Bmi1 may be a novel therapeutic strategy for the treatment of liver cancer." (PMID 23029524, 2012). "Collectively, BMI1 may be a potential target for the diagnosis and therapy of hepatic cancers." (PMID 32987767, 2020). "We propose that before the recognized oncogenic pathways are activated, four key DEGs (BMI1, NOP56, UBE2E1, and FAM98A) are aberrantly expressed, revealing the different prognoses of patients with liver cancer." (PMID 38515119, 2024). "The expressions level of miR-200b and BMI1 in HCC tissues and human liver cancer cell lines were analyzed by qPCR." (PMID 26919246, 2016). "By contrast, we detected significant upregulation of BMI1 in 66.7% (cohort 1: 24/36; cohort 2: 4/6) of HCC tissues and in all four human liver cancer cell lines." (PMID 26919246, 2016). "Interestingly, knockdown of Bmi1 inhibits cancer cell growth in vivo, and it has been recently proposed that this gene may be a potential target for innovative treatments against human liver cancer." (PMID 26161998, 2015).
liver cancer (continued). "Given that BMI1 is a validated functional SALL4 downstream effector in diverse malignancies, including liver cancer, we first examined whether Bmi1 expression is elevated in AY-Sall4 liver compared with AY-GFP control livers." (PMID 40932240, 2025). "Importantly, Napabucasin treatment impaired spheroid formation of liver cancer stem cells and downregulated the expression of stemness genes such as SOX2, BMI-1, Nanog, and c-Myc." (PMID 38326371, 2024). "Importantly, Napabucasin treatment impairs spheroid formation of liver cancer stem cells and downregulates the expression of stemness genes such as SOX2, BMI-1, Nanog, and c-Myc." (PMID 31277685, 2019). "Down-regulated expression of the stemness genes Bmi-1, c-Myc and Nanog was also detected, which indicated that pimozide inhibited the self-renewal capacity of HCC cancer stem-like cells and might be preferable to conventional chemotherapy for targeting liver cancer stem/stem-like cells." (PMID 26061710, 2017).
brain tumor (15 papers, 2006 to 2025). "Using Ink4a/Arf locus/BMI1 deficient NSCs stably expressing EGFRvIII, BMI1 was demonstrated to be important for the growth of brain tumours and overall survival following stereotactic injection of the cells into the brain of mice." (PMID 33432111, 2021). "This is the first study that evaluates the Bmi-1 gene expression by real-time PCR in various types of pediatric brain tumors in association with clinicopathological and prognostic significance." (PMID 23984324, 2013). "In univariate survival analysis of the pediatric brain tumors, a significant association of high expression of the Bmi-1 with patient survival was demonstrated." (PMID 23984324, 2013). "The results demonstrated that the expression level of the Bmi-1 was high in all types of the pediatric brain tumors, suggesting that the Bmi-1 gene expression is related to the incidence of pediatric brain tumors." (PMID 23984324, 2013). "As it is so widely expressed, the Bmi-1 expression cannot be used as a specific marker for pediatric brain tumors." (PMID 23984324, 2013). "In this study, the Bmi-1 gene expression, clinicopathological, and prognostic significance in a series of pediatric brain tumors were examined." (PMID 23984324, 2013). "In this study, to our knowledge, for the first time, we describe the Bmi-1 gene expression in various types of pediatric brain tumors." (PMID 23984324, 2013). "The Bmi-1 gene expression in various types of pediatric brain tumors compared to normal brain tissue was 4.85-fold (P = 0.009)." (PMID 23984324, 2013). "In primary brain tumor samples, Bmi1 expression was marked in 16/19 (84%) of GBM, 5/7 (71%) of oligodendroglioma and 3/7 (42%) of astrocytoma." (PMID 19823589, 2009). "As the Ink4a/Arf locus is frequently deleted in brain tumors, the role of Bmi1 overexpression in GBM cells appears to be distinct from its repression of the Ink4a/Arf locus." (PMID 19823589, 2009). "Our results demonstrated that increased expression of the Bmi-1 in pediatric brain tumors may be important in the acquisition of an aggressive phenotype." (PMID 23984324, 2013). "In addition, our study introduces the Bmi-1 expression as a strong and independent molecular marker of prognosis in pediatric brain tumors in addition to providing a specific target site for targeting therapy." (PMID 23984324, 2013). "The Bmi-1 gene expression, clinic pathological and prognostic significance in a series of pediatric brain tumors were examined by real-time PCR method in 56 pediatric brain tumors." (PMID 23984324, 2013). "Also it has been postulated that the Bmi-1 plays a role in self-renewal of cancer stem cells, so high expression of the Bmi-1 correlates with greater capacity of self-renewal and might represent the tumorigenesis and poor prognosis in pediatric brain tumors." (PMID 23984324, 2013). "Recently, the small‐molecule Bmi‐1 inhibitor PTC209, which exhibits selective post‐transcriptional properties, has shown promising therapeutic results in suppressing Bmi‐1 expression and mitigating self‐renewal in brain tumor cells." (PMID 39791545, 2025). "Multivariate Cox proportional hazards regression analysis demonstrated that high expression of the Bmi-1 in pediatric brain tumors was a predictor of short overall survival, independent of high or low grade tumors." (PMID 23984324, 2013). "Notably, we could confirm BMI1 and EZH2 down-regulation in the brain tumor during the treatment period and their reactivation 15 days post-treatment in an animal showing relapse." (PMID 31934644, 2020). "The Bmi-1 expression as a prognostic marker in pediatric brain tumors has not been indicated." (PMID 23984324, 2013). "The role of BMI1 in alternative splicing has been described in epithelial-to-mesenchymal transition (EMT), but not in brain tumours." (PMID 34316702, 2021).
myelodysplastic syndrome (14 papers, 2007 to 2024). A clonal hematopoietic disorder characterized by dysplasia and ineffective hematopoiesis in one or more of the hematopoietic cell lines. "In this study, we found that the patients of both myelodysplastic syndromes and chronic myeloid leukaemia with BMI1 overexpression had a higher risk in malignant myeloid progression." (PMID 24571310, 2014). "Moreover, Bmi-1 has recently been shown to be a useful molecular marker for predicting occurrence and prognosis in high-susceptibility cancer syndromes such as myelodysplastic syndrome." (PMID 17711569, 2007). "Similar to Bmi-1, Sall4 expression has been reported in numerous hematological malignancies, including myelodysplastic syndromes, AML, chronic myelogenous leukemia and precursor B cell lymphoblastic lymphoma." (PMID 28122538, 2017). "Moreover, BMI1 overexpression is frequently observed in myelodysplastic syndrome (MDS) patients harboring RUNX1 mutations." (PMID 24348510, 2013).
oral cancer (14 papers, 2007 to 2026). "Thus, our findings connecting BMI1 overexpression to increased oxidative stress during early-stage OSCC demonstrate that BMI1 accelerates another important feature of human oral cancers." (PMID 41385756, 2026). "Although Bmi-1 is an important target of miR-203-induced apoptosis in YD-38 human oral cancer cells, they also suggested that miR-203 might regulate other genes." (PMID 35898889, 2022). "Bmi1 that is one of members of the polycomb group transcription repressors involves in oral cancer." (PMID 32280305, 2020). "In addition, in a case of the use of the genetic lineage tracing, in vivo contribution of Bmi1 to regulate the stemness of oral cancer stem cells such as its self-renewal and tumorigenic potentials has been obviously illustrated." (PMID 32280305, 2020). "Kang found that Bmi-1 may act through a p16INK4A-independent pathways to regulate cellular proliferation during progression of oral cancer." (PMID 19228380, 2009). "Thus, our data suggest that Bmi-1 may act through p16INK4A-independent pathways to regulate cellular proliferation during oral cancer progression." (PMID 17179983, 2007). "On the other hand, it was demonstrated that the gene expression of Sox2 was upregulated in the Snail-overexpressing oral cancer cells, but the changes at the protein level were not significant (only Nanog, Bmi1, and ABCG2 were increased)." (PMID 35682836, 2022). "A similar result was observed for the treatment with A. paniculata in oral cavity cancer cells, significantly inhibiting oncogenicity and promoting radiosensitivity to oral cancer stem cells ALDH1+CD44+ through the upregulation of microRNA-218 and Bmi1 negative." (PMID 38248336, 2024).
squamous cell carcinoma (14 papers, 2010 to 2025). A carcinoma arising from squamous epithelial cells. "The aim of this study is to investigate the amplification and high expression of Bmi-1 and the associated clinicopathologic characteristics in esophageal adenocarcinoma and squamous cell carcinoma." (PMID 23078618, 2012). "Our study investigated the correlation between MCM4 and MCM7 expression and Ki-67, Bmi1, and cyclin E expression in esophageal adenocarcinoma, squamous cell carcinoma, and precancerous lesions." (PMID 27476776, 2016). "In conclusion, Bmi-1 was rarely amplified in esophageal adenocarcinoma, but highly expressed in esophageal adenocarcinoma and squamous cell carcinoma." (PMID 23078618, 2012). "Kaplan-Meier analysis compared by the log-rank test was used to calculate the effect of the high Bmi-1 expression in patients with esophageal adenocarcinoma and squamous cell carcinoma on overall survival." (PMID 23078618, 2012). "Of note, BCL11B was found to be co-expressed with the cancer stem cell marker BMI-1 in a subset of undifferentiated squamous cell carcinoma cases and cell lines." (PMID 20824091, 2010). "However, the expression of Bmi-1 in low- and high-grade dysplasia, esophageal adenocarcinoma and squamous cell carcinoma was evenly distributed throughout the full lesion." (PMID 23078618, 2012).
esophageal squamous cell carcinoma (13 papers, 2010 to 2023). Esophageal squamous cell carcinoma (ESCC) is a type of esophageal carcinoma (EC) that can affect any part of the esophagus, but is usually located in the upper or middle third. "High expression of Bmi-1, a key regulatory component of the polycomb repressive complex-1, has been associated with many solid and hematologic malignancies including esophageal squamous cell carcinoma." (PMID 23078618, 2012). "In esophageal squamous cell carcinoma, the data on the association between Bmi-1 expression and prognosis are limited and conflicting." (PMID 23078618, 2012). "An existing study documented the capacity of miR-218 to weaken the proliferative and metastatic abilities of esophageal squamous cell carcinoma cells via targeting BMI1." (PMID 35261819, 2022). "Esophageal squamous cell carcinoma, which exhibits high expression of BMI1 and EZH2, showed poor OS and disease-free survival." (PMID 29415665, 2018). "The esophageal squamous cell carcinoma group showed significantly high Bmi-1 expression compared with the squamous epithelium group (p = 0.008)." (PMID 23078618, 2012). "Nine of 34 cases of esophageal squamous cell carcinoma and 6 of 80 cases of squamous epithelium showed high expression of Bmi-1." (PMID 23078618, 2012). "Moreover, miR-218 suppresses the expression of B-cell-specific moloney murine leukemia virus insertion site 1 (BMI1) to subsequently impede cell proliferation and metastasis in esophageal squamous cell carcinoma." (PMID 35261819, 2022). "The objective of this study was to determine the expression of three stem cell markers, aldehyde dehydrogenase 1 (ALDH-1), B cell-specific Moloney murine leukemia virus integration site 1 (Bmi-1), and Nanog, in esophageal squamous cell carcinoma (ESCC) tissues." (PMID 25148045, 2014). "Elevated levels of Bmi-1 were also observed in adaptively radioresistant esophageal squamous cell carcinoma (ESCC) cells, where Bmi-1 silencing led to re-sensitization to radiation therapy." (PMID 36726797, 2023). "Expressions of BMI1 and p16INK4A, a downstream target of PcG, were analysed in 78 patients with histologically confirmed oesophageal squamous cell carcinoma (ESCC) after preoperative CRT by immunohistochemical staining." (PMID 23046527, 2012). "The objective of this study was to determine the level of Bmi-1 expression or its autoantibodies in human esophageal squamous cell carcinoma (ESCC) and to correlate it with clinicopathologic data." (PMID 20809956, 2010). "In esophageal squamous cell carcinoma, SNHG12 regulates BMI1 expression via sponging miR‐6835‐3p and enhances CTNNB1 stability via recruiting IGF2BP2." (PMID 32239639, 2020).